SIRPA (signal regulatory protein alpha)
Diseases named in the same sentence as SIRPA in open-access papers (continued):
Sharing a sentence is not in itself a finding about the gene and the disease.
bacterial infection (4 papers, 2013 to 2022). "We determined the deglycosylation of SIRPα after bacterial infection, after TNFα stimulation, and under control conditions." (PMID 23448224, 2013). "Interestingly, SIRPα was deglycosylated in monocytes after bacterial infection, whereas under TNFα stimulation and under control conditions only a very slight band of the deglycosylated form was observed." (PMID 23448224, 2013). "Here we show that immunoglobulin A (IgA) immune complexes (IgA-IC), which are present after bacterial infection of the lamina propria, are important for the induction of inflammation by the human CD103+SIRPα+ DC subset." (PMID 29491406, 2018). "Moreover, the transmembrane glycoprotein SIRPα was deglycosylated in monocytes, but not in PMNs, after bacterial infection." (PMID 23448224, 2013).
inflammation (4 papers, 2024 to 2025). Aberrant reaction of the microcirculation characterized by movement of fluid and leukocytes from the blood into extravascular tissues. "Importantly, treatment with either anti-CD47 or anti-SIRPα antibodies ameliorated liver inflammation and fibrosis by enhancing the clearance of necroptotic hepatocytes, suggesting that therapeutic blockade of the CD47-SIRPα axis acts as a strategy to dampen MASLD progression." (PMID 40494889, 2025). "Signal regulatory protein alpha (SIRPα), an inhibitory receptor that regulates ILC2 effector functions and AHR, has been shown to suppress ILC2 proliferation and cytokine secretion when engaged with CD47Fc, thereby mitigating AHR and lung inflammation in murine models." (PMID 40355861, 2025).
cardiovascular disease (3 papers, 2020 to 2022). "SIRPA and FBXL17 are both biologically plausible candidates for cardiovascular diseases and there are several possible explanations for why these associations have not been identified in European and Asian populations." (PMID 35165267, 2022).
blood cancers (2 papers, 2020). "In this regard there are several early phase clinical trials currently recruiting for combinations of CD47:SIRPα blockers + therapeutic antibodies for solid tumors and blood cancers." (PMID 33552071, 2020). "Early data emerging from these trials suggests that blood cancers are more sensitive than solid tumors to anti-CD47:SIRPα therapies." (PMID 33552071, 2020).
neurological disease (2 papers, 2019 to 2025). "Ten proteins showed co-localization with a neurological disease using both plasma protein abundance and plasma mRNA abundance (SIRPA, CTSH and CD33 with AD; and ASF1A, FCRL3, VEGFB, TYMP, PVALB, LMAN2 and CD5 with MS)." (PMID 40037332, 2025).
gastrointestinal tumors (1 paper, 2018). "Considering the negative effect of anti‐CD47 mAb on host immune cells, the augmentation of macrophage phagocytic activity by anti‐SIRPα mAb may constitute an effective treatment for human gastrointestinal tumors." (PMID 30460349, 2018). "SIRPα mAb augmentation of macrophage phagocytic activity may represent an effective treatment strategy for human gastrointestinal tumors." (PMID 30460349, 2018).
SIRPA also shares sentences with these, for which no sentence is quoted: Parkinson disease (4 papers); small cell lung carcinoma (4); aortic stenosis (3); cholangiocarcinoma (3); experimental autoimmune encephalomyelitis (3); ZIKV infection (3); angiosarcoma (2); chronic myelomonocytic leukemia (2); colorectal tumor (2); Crohn disease (2); Cutaneous T-cell Lymphoma (2); endometrial cancer (2); infectious disease (2); liposarcoma (2); liver cancer (2); metastasis (2); multiple myeloma (2); non-Hodgkin lymphoma (2); pancreatic ductal adenocarcinoma (2); rheumatoid arthritis (2); ulcerative colitis (2); abortion (1); acute liver failure (1); acute myocardial infarction (1); airway allergy (1); amyotrophic lateral sclerosis (1); arteriolosclerosis (1); astrocytoma (1); bipolar depression (1); bone sarcoma (1).
A further 61 diseases each share a sentence with SIRPA in 1 paper.